BRCA1 (BRCA1 DNA repair associated)
Diseases named in the same sentence as BRCA1 in open-access papers (continued):
Sharing a sentence is not in itself a finding about the gene and the disease.
tumor (continued). "In this study, we investigated the effect of estrogen on ER-negative BRCA1-deficient tumor progression by transplantation of tumor cells into the MFPs of NSG mice that did not receive ovariectomy." (PMID 29996906, 2018). "Anyhow, we believe a lot of the positive impact that might result from the introduction of the BRCA1/2 tumor testing, particularly because more patients should benefit from anti-PARP-1 targeted therapies or other similar new drugs coming soon." (PMID 29731958, 2018). "BRCA1 is a tumor suppressor, which is responsible for repairing damaged DNA." (PMID 28972307, 2017). "Moreover, Akt1-KD as well as the inhibition of HR proteins such as BRCA1 is known to induce autophagy and subsequently, increase tumor cell survival." (PMID 29156644, 2017). "An alternative explanation is that BRCAness exists when a DDR defect is present in a tumour in the absence of a germline BRCA1 or BRCA2 mutation." (PMID 29069866, 2017). "Furthermore, we establish the ubiquitin E3 ligase BARD1, a tumor suppressor and partner of BRCA1, as an indirect RNF4 target, regulated by PIAS1." (PMID 29180619, 2017). "However, if only one endogenous gene is used as a reference for the assessment of gene expression, we note that those tumor samples showed low BRCA1 mRNA expression." (PMID 27926510, 2017). "BRCA1 is a tumor-suppressing gene that is located upstream of NEAT1." (PMID 28118609, 2017). "In some studies, BRCA1 promoter methylation has been linked to the ER and PR status of the tumor, whereas others have not found a linkage between these two features." (PMID 28403857, 2017). "Both BRCA1-related cancers and TNBCs show induction of the tumor-initiating cells (TICs) phenotype." (PMID 28052035, 2017). "Currently small retrospective studies suggest that histology, stage of disease, loss of BRCA1 function, MDR-1 tumor expression may be associated with CNS progression in very small series of patients." (PMID 28467804, 2017). "Moreover, treatment with acetaldehyde in BRCA1‐ and BRCA2‐deficient mouse tumor models and patient‐derived tumor xenografts in vivo results in regression of tumors." (PMID 28835508, 2017). "Gains in 10p have further differentiated triple-negative cancers, and in 17q25 have distinguished BRCA1-mutated tumours." (PMID 28351365, 2017). "Importantly, a related Brca1−/− mouse tumor cell line, which acquired olaparib resistance as a result of 53BP1 inactivation, also showed remarkable sensitivity to acetaldehyde in viability assays." (PMID 28729482, 2017). "Overall, hsa-miR-361-3p has been found over-expressed in TNBCs with respect to other subtypes and healthy controls; and used to discriminate BRCA1/2 mutation carriers and non-carriers tumours." (PMID 28351365, 2017). "Moreover, since BRCA1 is a well-studied tumor suppressor gene and involved in signal transduction and the repair of DNA damage, 11 CpG sites in BRCA1 promoter were subjected to pyrosequencing." (PMID 28199384, 2017). "Reduced BRCA1 expression was associated with high tumor grade and negative hormone receptors (estrogen receptor, progesterone receptor and Her2)." (PMID 28863181, 2017). "Using tumor SGZ classification and comparison with germline assay results, we identified 20 somatic BRCA1/2 mutation cases, a slightly larger number than the 18 candidate somatic-BRCA1/2-mutated patients in our previous report." (PMID 28525389, 2017). "They divided the tumours into two groups, depending on the level of expression of miRNAs and BRCA1." (PMID 29021870, 2017). "In addition, we found a correlation between the methylation levels in tumors and tumor-distant tissues for BRCA1 (r = 0.826, p < 0.001) and ESR1 (r = 0.555, p = 0.017)." (PMID 28403857, 2017). "BRCA1 positive cases more often had Nestin positive tumours, compared with cases without BRCA1 germline mutations, OR (odds ratio) 8.7 (p < 0.0005, Series III), with a sensitivity of 62% and specificity of 84%." (PMID 28439082, 2017).
tumor (continued). "BRCAness has been defined as a phenocopy of BRCA1 or BRCA2 pathogenic mutations, with the existence of an HRR tumour defect in the absence of a BRCA1 or BRCA2 germline mutation." (PMID 29259228, 2017). "Moreover, Brca1−/− mouse tumor cells also displayed acetaldehyde sensitivity relative to Brca1+/+ control cells." (PMID 28729482, 2017). "Application of this model allowed the identification of additional tumours with alteration of BRCA1 or BRCA2, which could have selective therapeutic sensitivity to PARP inhibition." (PMID 28491135, 2017). "Mutations in BARD1 gene may lack the RING domain that interacts with BRCA1, thereby affecting the sub-cellular localization and retention of BRCA1 and compromising tumor suppressor activity; these mechanisms may contribute to carcinogenesis." (PMID 28794477, 2017). "Tumor suppressor functions of BRCA1 are thought to be mediated by the BARD1-BRCA1 heterodimer which is an E3 ubiquitin ligase implicated in DNA repair and in other essential functions for maintaining genomic stability, as homologous recombination, centrosome duplication and mitotic spindle assembly." (PMID 29292755, 2017). "Besides age at diagnosis, none of the clinicopathological variables tested in univariate analysis (FIGO stage, residual tumor, lymph node status, neoadjuvant chemotherapy and distant metastasis) correlated with BRCA1 promoter hypermethylation." (PMID 29137324, 2017). "Furthermore, we demonstrate that the profile of BRCA1 gene expression was significantly different between normal vs. tumor tissue." (PMID 27926510, 2017). "BRCA1 is an essential tumor suppressor involved in DSB repair, preserving genome stability." (PMID 29267250, 2017). "However, later studies showed that although BAP1 was a tumor suppressor that played a role in BRCA1-mediated processes, it performed BRCA1-independent functions as well." (PMID 28404968, 2017). "Given that Rad51 and BRCA1 play a central role in HR-mediated DSB repair and govern the response of tumor cells to cisplatin, we wondered whether let-7e regulates BRCA1 and Rad51 expression in EOC." (PMID 28376831, 2017). "Recently, reduced expression of the BRCA1 and PTEN tumor suppressors have been implicated in the synaptic deficits observed in AD66, 67, contributing to an emerging hypothesis that tumor suppressor dysfunction underlies AD pathophysiology." (PMID 28496137, 2017). "This ability to accurately predict response within BRCA1/2 mutant tumor cells indicates future that trials implementing the signature could be performed on BRCA1/2 cohorts already being treated with PARP inhibitors before expanding to larger cohorts." (PMID 28649435, 2017). "In summary, BRCA1/2-mutation was significantly associated with improved PFS for studies stratified according to study quality, study design, number of research center, tumor histology and study region." (PMID 27690218, 2017). "This suggests a high penetrance and a high risk of BC for the carriers; the pathogenic mutations in genes other than BRCA1/2 do not appear to be linked to OC, since all these patients have BC, only 2 of whom developed OC as second tumor." (PMID 28423363, 2017). "Furthermore, its potency against BRCA1/2 wild type expressing tumours warrants strong activity against tumors in the advanced stages where BRCA1/2 becomes largely heterogeneous." (PMID 28800752, 2017).
tumor (continued). "On the other hand, we observed that the African ancestry component among individuals without BRCA1/BRCA2 mutations was associated with higher tumor grade (p = 0.008)." (PMID 27741520, 2016). "The association between TNBC and prevalent BRCA1 mutations was independent of the simultaneous consideration of family history, tumor histology and tumor grade in a multiple logistic regression model." (PMID 27553291, 2016). "The BRCA1 protein is responsible for DNA repair, signal transduction, and tumor suppression." (PMID 30460281, 2016). "Similarly, the CtIP protein, which interacts with the BRCA1 tumor suppressor, is also thought to have tumor suppression activity." (PMID 27058754, 2016). "In addition to its role in resection, CtIP is one of several proteins that bind the C-terminal BRCT repeats of the BRCA1 tumor suppressor." (PMID 27058754, 2016). "BRCA1 is a multifunctional tumour suppressor, which has a key role in mammary tumorigenesis." (PMID 27043660, 2016). "Two of 16 cases of this rare tumor (12.5%) were shown to have the BRCA2 Portuguese founder mutation, with a 14.3% (2/14) frequency observed when considering only the samples with mutations and those in which all BRCA1/BRCA2 coding regions were analyzed." (PMID 27532258, 2016). "The exclusion of promoter methylation analysis from this study was due to the fact that in the cases with hypermethylation (almost exclusively TNBCs) the BRCA1:ID4 ratio and protein presence and localization were able to classify the tumor into the appropriate BRCA1 category." (PMID 27077368, 2016). "Here they define BRCAness as “a situation in which an HR defect exists in a tumor in the absence of a germline BRCA1 or BRCA2 mutation”." (PMID 27756336, 2016). "Furthermore, immunohistochemistry studies demonstrated that BRCA1/2-mutated tumors exhibited significantly increased CD3+ and CD8+ TILs, as well as elevated expression of PD-1 and PD-L1 in tumor-associated immune cells compared to HR-proficient tumors." (PMID 26871470, 2016). "Although mice bearing a CtIP missense mutation that ablates the BRCA1/CtIP interaction are not tumor prone, CtIP is commonly thought to function as a tumor suppressor, in part based on a previous study of mice bearing a null Ctip allele." (PMID 27058754, 2016). "Moreover, it would be more interesting to study women with BRCA1 and BRCA2 mutations separately due to their differences in tumor characteristics." (PMID 27129401, 2016). "However, there was a significant relation between BRCA1 promoter methylation level and tumor stage, and size." (PMID 27027444, 2016). "Promising activity of trabectedin was also shown in chemotherapy-pretreated hereditary ovarian cancer patients, although similar rates of tumor responses were observed in BRCA1/2 mutation carriers vs. non-carriers." (PMID 27555886, 2016). "Tumour BRCA1 promoter methylation has been reported to predict response to platinum based chemotherapy agents and Poly(ADP-ribose) polymerase (PARP) inhibitors, therefore methylation status could potentially influence treatment decisions." (PMID 27463681, 2016).
tumor (continued). "In conclusion, taking into account the implications for both the individuals and their family members, we recommend that patients with these neoplasias should be offered BRCA1/BRCA2 genetic testing and we here show that it is feasible to test for founder mutations in archival tumor tissue." (PMID 27532258, 2016). "More intriguingly, RAD52 depletion is also synthetically lethal with defects in BRCA1, a tumor suppressor that acts upstream of BRCA2 in HR and at the branch point in the DSB repair that promotes homology-directed DNA repair through HR or SSA over the NHEJ (non-homologous end joining)." (PMID 27434671, 2016). "Due to the lack of the ring binding domain, BARD1β does not contain the binding site necessary for interaction with BRCA1 and may display oncogenic effect via affecting BARD1/BRCA1 tumor suppressor function either independent or dependent on FL BARD1 protein." (PMID 27197561, 2016). "BRCA1 promoter was methylated in 42.5% of tumor tissue compared to 35% in control normal tissue." (PMID 27413552, 2016). "We next assessed whether, in addition to our genetic experiments, preventive pharmacological RANKL inhibition could also be used to mitigate tumor development in a Brca1 mutant mouse background." (PMID 27241552, 2016). "For one of them, showing positive BRCA1 methylation, high T-lymphocyte infiltration could be assessed because a matched tumor section of the same patient was available." (PMID 27756336, 2016). "Among tumours with ER, PR and HER2 data, 96.7 % were ER+, 86.8 % were PR+ and 83.4 % were HER2− in BRCA2 mutation carriers, vs. 90.3 % ER+, 78.6 % PR+ and 89.5 % HER2− in BRCA1 mutation carriers." (PMID 26857456, 2016). "These included specific types of somatic mutations (e.g. BRAF), germline mutations (e.g. BRCA1), biomarkers (e.g. CA125), risk factors (e.g. UV exposure) prognostic features of the tumor (e.g. tumor infiltrating lymphocytes), and specific clinical features (e.g. associated ascites)." (PMID 27629872, 2016). "In the multivariable model, after adjusting for age, tumor grade and PD-L1, BRCA1 mutation status was no longer significantly associated with AR expression ⩾1 or >10%." (PMID 28721372, 2016). "The majority of lung tumors do not exhibit mutations in BRCA1 or 2 genes (BRCA1 or 2 is mutated in 1.8%-11.2% of cases depending on the data set and tumor type)." (PMID 26959114, 2016). "Because of the involvement of its tumor suppressor activity in cell cycle transcription, DNA damage response and chromatin remodeling, a dysregulation in BRCA1 following aberrant methylation could result in genomic instability." (PMID 27556302, 2016). "We next explored whether the ability of metformin to reduce tumor-initiating capacity in BRCA1 one- hit cells correlated with a capacity to alter the highly anabolic (biosynthetic) signature driven by BRCA1 haploinsufficiency." (PMID 27259235, 2016). "This represents an alternative approach to the use of FFPE materials for the identification of BRCA1 and BRCA2 tumor mutations which may be of germline or somatic origin." (PMID 27793035, 2016). "Emerging evidence from epidemiologic studies, from human tissue culture model systems and from murine studies supports a continuum of tumor suppression where BRCA1 expression levels might be tightly correlated with function." (PMID 27534398, 2016). "BRCA1 and BRCA2 are tumor suppressors that are commonly mutated or depleted in hereditary and sporadic breast cancers, and have important roles in homologous recombination (HR), a template directed pathway that accurately repairs DNA lesions affecting both strands of the DNA duplex." (PMID 27434671, 2016).
tumor (continued). "Therefore, we observe an apparent paradox between BRCA1 tumour suppressor role and its functions in Pol-I transcription." (PMID 27589844, 2016). "Thus, we concluded that metformin treatment reduced the tumor-initiating (self-renewal) capacity of breast epithelial BRCA1 one-hit cells, whereas BRCA1 wild-type cells were mostly resistant at similar doses, which is indicative of a wide therapeutic index." (PMID 27259235, 2016). "This is in keeping with the assumption that not all BRCA1 mutations result in the same dysfunction and our own data showing that not all BRCA1 mutant tumours are classified as “NFκB on”." (PMID 26943587, 2016). "All patients with germline mutations in BRCA1 (but none of the BRCA2-carriers) were predicted to carry a tumor with a basal-like subtype and the variants were all listed as known pathogenic in ClinVar36." (PMID 27901097, 2016). "This lead to hope for improved survival based on projection of observations of tumours in patients without demonstrated BRCA1 mutations, assuming that their biology and response to treatment were similar." (PMID 27087880, 2016). "ALDH1 positivity was thus associated with a BRCA1 defect and we additionally find this association to be independent of tumor sub-type unlike the CD44/24 profile." (PMID 27229859, 2016). "However, there was a significant relationship among BRCA1 methylation level and tumor stage (R = 0.6165, P < 0.0001), and tumor size (R = 0.7328, P < 0.0001)." (PMID 27027444, 2016). "Thus, structural and functional analysis of Abraxas and BRCA1 interaction is necessary to facilitate the understanding of Abraxas-mediated BRCA1 signaling in tumor suppression." (PMID 26778126, 2016). "The BRCA1 BRCT domains are essential for BRCA1's tumor suppressor function." (PMID 26848770, 2016). "To determine how specific the genetic complementation is between Brca1 and Cobra1, we first asked whether genetic ablation of other growth-arresting tumour suppressor genes could rescue the developmental defects associated with CKO." (PMID 26941120, 2016). "The association between TNBC status and presence of BRCA1 mutations was independent of the simultaneous consideration of family phenotype, tumor histology, and tumor grade in a multiple logistic regression model." (PMID 27553291, 2016). "They showed that LOH occurred in two BRCA2 and one BRCA1 tumor." (PMID 27836010, 2016). "First, BRCA1 regulates fatty acid biosynthesis both in adipose tissue and also in tumor cells." (PMID 26943589, 2016). "The function of BRCA1 in HR-mediated repair contributes to its tumor suppressor activity." (PMID 26909613, 2016). "In this work, we focus on the post-transcriptional regulation of the BRCA1 gene, a major tumor suppressor and regulator of double-stranded break DNA repair and show that its mRNA is targeted by many members of the miR-15/107 group at a site located within the CDS." (PMID 26257769, 2015). "BRCA1 is established as a tumor suppressor and functions primarily by maintaining genome integrity." (PMID 26623723, 2015). "All BRCA1, RAD17 and Chk1 mutations are rarely detected in sporadic tumours." (PMID 25650659, 2015). "In addition to driving TNBC tumor formation, BRCA1-IRIS overexpression drives their intrinsic and acquired paclitaxel resistance, partly by activating autocrine signaling loops EGF/EGFR-ErbB2 and NRG1/ErbB2-ErbB3." (PMID 25583261, 2015). "We conclude that tumor DNA methylation data alone has potential to be used in prediction of BRCA1 variant pathogenicity but is not independent of estrogen receptor status and grade, which are used in current multifactorial models to predict pathogenicity." (PMID 26727311, 2015).